OR51B2 (olfactory receptor family 51 subfamily B member 2)
Description:
Odorant receptor.
Synonyms: OR51B1P; HOR5'Beta3
Tractability: Antibody: UniProt places it where antibodies can reach, with medium confidence; UniProt predicts a signal peptide or a membrane-spanning region; its Gene Ontology location is reachable by antibodies, with medium confidence. PROTAC: UniProt records ubiquitination sites on it.
Gene: Protein-coding gene on chromosome 11 (5,323,359 to 5,324,297, reverse strand). Ensembl gene ENSG00000279012.
Subcellular location: Cell membrane
Pathways (Reactome):
Sensory Perception: Expression and translocation of olfactory receptors
Gene Ontology:
Molecular function: olfactory receptor activity; G protein-coupled receptor activity; signaling receptor activity
Biological process: cellular response to lipid; detection of chemical stimulus involved in sensory perception of smell; G protein-coupled receptor signaling pathway; system process
Cellular component: plasma membrane; membrane
Genetic constraint (gnomAD): Loss-of-function variants: 0 observed, 0.33 expected, observed/expected ratio (o/e) 0, 90% interval 0 to 1.86. That is too few expected variants to judge how well the gene tolerates losing a copy. Missense variants: 463 observed, 398.52 expected, observed/expected ratio (o/e) 1.16, 90% interval 1.08 to 1.25. Synonymous variants: 158 observed, 142.83 expected, observed/expected ratio (o/e) 1.11, 90% interval 0.97 to 1.26.
Homologues: Paralogues in human: OR51B6 (68% identical), OR51B5 (66% identical), OR51B4 (65% identical), OR51V1 (50% identical), OR51G1 (49% identical), OR51G2 (48% identical), OR51Q1 (46% identical), OR51F2 (46% identical), OR51C1 (46% identical), OR51A4 (45% identical), OR51M1 (45% identical), OR51I2 (45% identical), and 39 more.
Diseases named in the same sentence as OR51B2 in open-access papers:
OR51B2 is named in the same sentence as 1 disease in open-access papers, as found by Europe PMC text mining. Sharing a sentence is not in itself a finding about the gene and the disease.
OR51B2 shares sentences with these, for which no sentence is quoted: tumor (1 paper).